GSTP1 (glutathione S-transferase pi 1)
Diseases named in the same sentence as GSTP1 in open-access papers (continued):
Sharing a sentence is not in itself a finding about the gene and the disease.
prostate carcinoma (continued). "Promoter hypermethylation leading to epigenetic silencing of GSTP1 gene expression is frequently detected in prostate cancer cells, the most commonly diagnosed type of malignancy among men in Western European countries and the second cause of cancer-related deaths among men worldwide." (PMID 25076909, 2014). "Studies showed that green tea polyphenols are excellent candidates for the chemoprevention of prostate cancer reexpression of GSTP1 in human prostate cancer cells, as they induce GSTP1 expression through demethylation of its promoter in human prostate cancer cells." (PMID 25389438, 2014). "It is likely that GSTP1 enzyme activity in prostate cancer tissues has been reduced." (PMID 23977100, 2013). "Glutathione S-transferase pi 1 (GSTP1) is known to be silenced by hypermethylation of deoxycytidine residues within CpG dinucleotides within its upstream regulatory region in nearly all human prostate cancers." (PMID 24312188, 2013). "In conclusion, our findings of frequent APC and GSTP1 methylation in NTAT and their association with mortality from prostate cancer support the notion that changes in gene methylation are an early event in prostate carcinogenesis and play a role in cancer progression." (PMID 23874531, 2013). "Prevalence of GSTP1, PON1/192, PON1/55 and CYP17 polymorphisms and risk of prostate cancer (Pca)." (PMID 24040147, 2013). "GSTP1 methylation has been evaluated independently as a biomarker of prostate cancer n urine sediments, revealing its ability to differentiate between BPH and prostate cancer; furthermore, the frequency of high methylation status correlates strongly with stage III and IV disease." (PMID 22641253, 2012). "As examples, methylation of the CDKN2A promoter has been detected in sputum of smokers up to 3 years before they were diagnosed with cancer, GSTP1 has been used in prostate cancer detection, and RASSF1A can be detected in serum from gastric colorectal adenocarcinoma patients." (PMID 22570110, 2012). "GSTP1 is likely the most studied epigenetic lesion in relation to prostate cancer." (PMID 22672250, 2012). "Most importantly, we provide evidence that the increased potency of 5-aza-CdR compared to Zebularine in prostate cancer cells is closely related to its demethylating activity and identified GSTP1 as a potentially useful biomarker for assessing DNMTi efficacy in prostate cancer." (PMID 21980513, 2011). "Although past studies have shown that 5-aza-CdR was able to demethylate and re-express GSTP1 in prostate cancer cells, our results are the first to demonstrate that GSTP1 methylation and protein status was indicative of 5-aza-CdR treatment efficacy using a daily low-dose treatment regime." (PMID 21980513, 2011). "No mutations or deletions have been reported for GSTP1 gene in prostate cancer; however the gene is inactivated and both alleles are commonly methylated." (PMID 22191037, 2011). "GSTP-1 may be used as a screening method for prostate cancer detection and is a biomarker for diagnosis." (PMID 24213111, 2011). "Given the high frequency and specificity of GSTP1 DNA methylation in prostate cancer, we investigated whether GSTP1 is a useful marker of DNMTi treatment efficacy." (PMID 21980513, 2011). "The purpose of this study was to conduct a meta-analysis of the sensitivity and specificity for prostate cancer detection of glutathione-s-transferase–π (GSTP1) methylation in body fluids (plasma, serum, whole blood, urine, ejaculate, and prostatic secretions)." (PMID 21654682, 2011). "Investigation of the GSTP1 gene did not reveal any significant association between heterozygous GSTP1 genotype (Ile/Val) and prostate cancer." (PMID 19265530, 2009). "Some studies, which combined data from other genotypes, have shown that the concurrent lack of GSTM1/GSTT1 and GSTP1 genes posed a significantly increased risk of prostate cancer." (PMID 19265530, 2009).
prostate carcinoma (continued). "In addition, methylation of GSTP1 is highly specific to prostate cancer, rarely detected in other tumours." (PMID 17453001, 2007). "Therefore, the efficacy of GSTP1 as a prognostic biomarker of clinically significant prostate cancer would undoubtedly be improved with the discovery of further epigenetic targets in this disease." (PMID 17453001, 2007). "For example, the results of a meta-analysis substantiated the high specificity of promoter methylation of GSTP1 in cell-free DNA (cfDNA) for the diagnosis of prostate cancer, and this could be used to more precisely evaluate the prognosis of patients with this type of cancer." (PMID 39125992, 2024). "In all, the molecular characterization of prostate cancer genes and gene function hints that several distinct molecular subsets (ERG+ vs. ERG–, PTEN+ vs. PTEN–, GSTP1+ vs. GSTP1–) may be more or less prevalent among prostate cancer cases in Black versus White men." (PMID 35104804, 2022). "Thus, the over-representation of GSTP1-positive prostate cancer in Black men may render them less responsive to taxane chemotherapy, which is the preferred chemotherapy for advanced, lethal metastatic castration resistant prostate cancer." (PMID 34191807, 2021). "In support of this hypothesis, the aberrantly methylated GSTP1 CGI promoter acquires little methylation when it is ectopically introduced into prostate cancer cells but gains of methylation were stimulated by prior in vitro seeding of low-level DNA methylation." (PMID 33514701, 2021). "Proteomics analysis revealed that GSTP1 is overexpressed in cisplatin- and irinotecan-resistant glioma, fluorouracil (5-FU)- and cisplatin-resistant gastric cancer cells, doxorubicin-resistant prostate cancer cells, and adriamycin-resistant breast cancer cells." (PMID 33946704, 2021). "Keeping in mind JNK’s roles in the apoptosis, proliferation, migration and DNA repair in prostate cancer, as well as the relationship between JNK and the androgen receptor, it might be hypothesized that GSTP1 polymorphic variants might have different impacts on PC development." (PMID 32183092, 2020). "Limited to GSTP1, we also conducted analyses stratified by the Gleason score, to evaluate more aggressive (score of 4 + 3, or at least 8) and less aggressive (score of 6 or 3 + 4) prostate cancers, and by ward (Ward I and Ward II), for the purpose of validation." (PMID 31666119, 2019). "GSTP1 methylation in the first and in the second negative biopsy was associated with prostate cancer detection [OR per 1% increase: 1.14 (95% CI 1.01–1.29) for the second biopsy and 1.21 (95% CI 1.07–1.37) for the highest methylation level (first or second biopsy)]." (PMID 31666119, 2019). "Indeed, a commercial test (ConfirmMDx for Prostate Cancer, MDx Health), based on APC (Adenomatous Polyposis Coli), GSTP1, and RASSF1 (Ras Association (RalGDS/AF-6) Domain Family Member 1) hypermethylation in cancer-negative biopsies, offers a negative predictive value of 90%39." (PMID 28084441, 2017). "This meta-analysis showed that GSTP1 Ile105Val polymorphism might not be significantly associated with overall prostate cancer risk." (PMID 23977100, 2013). "It should be noted that the gene GSTP1 was in an association with ferritin H gene, gene LHB was significantly with testosterone and estradiol levels and special CYP3A/KLK3 genotypes increased metastatic disease while the expression of CYP3A in prostate cancer was regulated by androgen." (PMID 24146788, 2013). "However, the results in our study does not support that smoking modifies the effect of GSTP1 Ile105Val polymorphism on prostate cancer risk." (PMID 23977100, 2013). "GSTP1 may play a vital role in the development of prostate cancer." (PMID 23977100, 2013). "It suggested that smoking might not significantly modify the effect of GSTP1 polymorphism on the risk of prostate cancer." (PMID 23977100, 2013).
prostate carcinoma (continued). "Nearly 96% of primary prostatic adenocarcinomas display extensive hypermethylation and thus loss of function of the GSTP1 gene, however recent data showed no associated risk for sporadic or familial prostate cancer with polymorphism in codon 105 of the pi variant (GSTP1 I105v)." (PMID 24282788, 2013). "Similarly to the experiments performed in HeLa cells; we then determined whether FAIM and GSTP1 represent miR-133b target genes in prostate cancer cells." (PMID 22532850, 2012). "In addition, GSTP1 methylation is correlated with Gleason grade and prostate cancer volume, suggesting that quantitative GSTP1 methylation may be of prognostic significance." (PMID 20671914, 2010). "The possibility to detect GSTP1-HM in the blood serum from prostate cancer patients and recent reports about the prognostic significance of its detection indicate, that the determination of GSTP1-HM in blood serum may represent a very promising tool for the follow-up of prostate cancer patients." (PMID 16803634, 2006). "Promoter hypermethylation of the detoxifying glutathione-S-transferase P1 gene (GSTP1) is the most common DNA alteration of primary prostatic carcinoma and has already been assessed in prostatic tissue, lymph nodes and bodily fluids of prostate cancer patients by our own group and others." (PMID 16803634, 2006). "GSTP1‐1 is overexpressed in several cancers, including CLL, squamous cell carcinoma, ALL, and prostate cancer." (PMID 41179371, 2025). "Specifically, it significantly decreased methylation at the promoter regions of BRCA1, GSTP1, and Eph receptor B2 (EPHB2) in DU-145 and PC-3 prostate cancer cell lines, leading to cell cycle arrest in the G0/G1 phase." (PMID 41226811, 2025). "Intuitive and biologically interpretable methylation state thresholds are inferred and DMCs are identified, including those related to genes such as GSTP1, RASSF1 and RARB, known for their role in prostate cancer development." (PMID 39661598, 2024). "In prostate cancer, highly expressed piRNA-31470 directs DNMT1 and DNMT3α to bind to CpG islands of glutathione S-transferase pi 1 (GSTP1) via PIWIL4." (PMID 36882835, 2023). "piR-31,470, highly expressed in prostate cancer, forms a complex with PIWIL4 and maintains the hypermethylation of GSTP1, inactivating it and reducing its expression." (PMID 38031146, 2023). "More recently, an assay that evaluates the methylation of GSTP1, SFRP2, IGFBP3, IGFBP7, APC and PTGS2 genes to specifically identify individuals with a severe probability of developing prostate cancer has been proposed." (PMID 37511475, 2023). "For example, glutathione S-transferase Pi 1 (GSTP1) is involved in DNA protection and androgen receptor (AR) in prostate cancer." (PMID 35069913, 2022). "In a mouse model of early prostate cancer development induced by human MYC, Gstp1/2 also functions as a tumor suppressor." (PMID 34191807, 2021). "In a recent prospective study, the prognostic significance of promoter methylation of GSTP1 and APC in ctDNA was evaluated in castration‐resistant prostate cancer." (PMID 33942482, 2021). "In addition, a GSTP1 methylation assay based on a hypermethylated CpG island in the promoter of GSTP1 and frequently reported in tumor tissues from prostate cancer patients is under clinical test to improve the detection sensitivity, specificity, and accuracy of early prostate cancer diagnosis." (PMID 33708235, 2020). "Hypermethylation of the GSTP1 promoter leads to its expression in PCa patients compared with those with BPH, signifying its critical role in prostate cancer progression." (PMID 32906694, 2020). "Soy phytoestrogens, genistein, and daidzein showed the protective effect of soy against prostate cancer by promoting demethylation of GSTP1 and EPHB2 promoter regions in prostate cancer cells." (PMID 31597327, 2019).
prostate carcinoma (continued). "Second, the association between GSTP1 methylation and age was mainly due to seven cystoprostatectomy patients with much higher GSTP1 methylation levels than those found in non-tumor prostate tissues matched to prostate cancer tissues of 12 patients included in the study." (PMID 31666119, 2019). "Our preliminary results highlighted that hypermethylation of GSTP1, RARB, RASSF1, SCGB3A1 and CCND2 was highly tumour-specific in prostate cancer tissue." (PMID 27576364, 2016). "Our preliminary results, obtained in a single-institution study with limited enrolment, showed that the hypermethylation of GSTP1, RARB, RASSF1, SCGB3A1 and CCND2 was highly tumour-specific in prostate cancer tissue." (PMID 27576364, 2016). "Evidence from earlier studies has linked promoter hypermethylation of specific genes to pathogenesis and tumor progression in prostate cancer, e.g. APC, RARβ, and GSTP1." (PMID 24626295, 2014). "Several are known biomarkers for diagnosis and prognosis of prostate cancer (APC, GSTP1, KIT, PYCARD, PGDGRB, RARB, RARRES1, and TIMP1) and some though not biomarkers, were found to be dysregulated in the disease (CDKN1B, MMP7, and MMP9)." (PMID 24626295, 2014). "The hazard ratio (HR) of prostate cancer mortality was 2.38 (95% confidence interval: 1.23–4.61) for APC methylation, and 2.92 (1.49–5.74) for GSTP1 methylation in NTAT." (PMID 23874531, 2013). "For example, GSTP1, RASSF1A, RAR2 and LGALS3 promoters are frequently methylated in prostate cancer; while ARF, APC, and DAPK have been found methylated in bladder cancer." (PMID 25419445, 2012). "Biomarkers like GSTP1, APC and RASSF1 have demonstrated involvement with prostate cancer, with the latter two genes playing prominent roles in the field effect." (PMID 22672250, 2012). "We have shown that hypermethylation of RAR-2β, GSTP1, PDLIM4, and FLNC facilitates the diagnosis of prostate cancer with a sensitivity and specificity of 87.3% and 87.1%, respectively." (PMID 20671914, 2010). "Another study, which investigated the DNA methylation of GSTP1 across different ethnic groups, also found it universally hypermethylated in prostate cancer, but not significantly different in DNA methylation levels between ethnic groups." (PMID 36937425, 2023). "For example, the glutathione-S-transferase P1 (GSTP1) gene is hypermethylated in 70-80% of prostate cancer patients, but not in normal hyperplastic prostate tissues." (PMID 36817422, 2023). "The results showed that a positive GSTP1 methylation test was 94% accurate in diagnosing prostate cancer, and a negative test was 45% accurate." (PMID 36747996, 2023). "Absence of GSTP1 sensitizes prostate cancer cells to mutagenic damage by HAA carcinogens, and confers improved survival, despite increased genome damage, in response to chronic oxidant stress." (PMID 35104804, 2022). "In addition, Cur affected the expression of several other enzymes and genes, namely 5 CpGs in the promoter region of the Nrf2 gene in prostate cancer, the DLEC1 promoter in HT29 cells, the PAX1 promoter in cervical cancer, and the GSTP1 promoter." (PMID 35327559, 2022). "Promoter hypermethylation-mediated silencing of GSTP1 is only detected in intraepithelial neoplasia, prostatic adenocarcinoma, and fluids (plasma, serum, ejaculate, and urine) of patients with prostate cancer but is never detected in benign epithelium." (PMID 33628338, 2021). "In terms of GSTP1 positive prostate cancer, it is possible that some cases arise after induction of GSTP1 in luminal cells and without silencing the gene." (PMID 34191807, 2021). "Indeed, CNA burden has been previously shown to be a strong predictor of recurrence and survival in prostate cancer implicating methylation of GSTM2 and GSTP1 in the prognosis of prostate cancer patients via allowing for higher amount of genomic aberrations." (PMID 34871444, 2021).
prostate carcinoma (continued). "Our findings are also consistent with the results of previous studies on GSTP1 methylation in non-tumor tissue as a potential marker for prostate cancer." (PMID 31666119, 2019). "For GSTP1, the ORs for aggressive prostate cancer were similar or slightly higher compared to those for non-aggressive prostate cancer." (PMID 31666119, 2019). "Importantly, the level of methylated GSTP1 in plasma is a better predictor of the overall survival than prostate-specific antigen (PSA), which is used in most common prostate cancer tests." (PMID 31443448, 2019). "Second, the sample size was not sufficient to obtain strong evidence on the potential specificity of the GSTP1 methylation for aggressive prostate cancer (as opposed to non-aggressive cancers)." (PMID 31666119, 2019). "Despite the fact that GSTP1 methylation is certainly a good marker for prostate cancer, it is not currently used in clinical practice and further validation studies are needed." (PMID 27594734, 2016). "By contrast, the reduced expression and activity of GSTP1 are observed due to the hypermethylation of its promoter in hepatocellular carcinoma (HCC) and prostate cancer, although GSTP1 may also be detected in the corresponding non-tumorous tissues." (PMID 23426146, 2013). "However, two or multiple genes cohort such as GSTP1/LGALS3 or GSTP1/RARβ2/APC has been shown to be more specific and sensitive biomarkers for prostate cancer." (PMID 25419445, 2012). "For example, GSTP1 methylation is detected as low as one prostate cancer cell, but not specific to prostate cancer as the GSTP1 methylation is also present in breast and renal cancers." (PMID 25419445, 2012). "An initial test cohort of 30 prostate cancer-positive samples and 12 cancer-negative samples was used as basis for the development and optimization of an epigenetic multiplex assay based on the GSTP1, APC and RASSF1 genes, using methylation specific PCR (MSP)." (PMID 22672250, 2012). "Epimethylation of the GSTP1 gene is absent in normal prostate tissue and present in 6.4% of proliferative inflammatory atrophy, which is the precursor lesion of prostate cancer." (PMID 21867542, 2011). "Cells with a defective GSTP1 gene may become vulnerable to oxidants and electrophiles that can inflict genomic damage, which in turn may promote transformation of PIN to prostate cancer." (PMID 20671914, 2010). "Expression of GSTP1 is diminished or absent in prostate cancer, and this absence is tightly regulated by hypermethylation of the promoter CpG Island." (PMID 20671914, 2010). "Distribution of GSTP1, GSTT1 and GSTM1 genotypes in controls and patients with prostate cancer." (PMID 19265530, 2009). "Promotor methylation of the GSTP1 gene has been detected in the urine and ejaculates of men with prostate cancer but not in patients with benign prostatic hyperplasia." (PMID 19662228, 2008). "Statistically significant differences were found for the methylation status of GSTP1 between prostate cancer and both BPH and histologically normal adjacent tissues (P<0.0001)." (PMID 17453001, 2007). "For instance, Glutathione S-transferases (GSTP1) implicating carcinogen defenses, growth-factor-signaling pathways (NKX3.1, PTEN) that regulate the growth and survival of prostate cells, and AR, which is a transcription factor, are critical determinants of prostate cancer phenotype cells." (PMID 39595075, 2024). "The locus-specific methylation of three genes (GSTP1, RNF219, and KIAA1539, also known as FAM214B) in the total pool of blood cell-free DNA, including cell-free DNA from plasma and cell-surface-bound DNA, of patients with prostate cancer and healthy donors was studied on the MiSeq platform." (PMID 36672380, 2023). "In addition, we also propose that SPINT2 (OR: 1.05, 95% CI 1.03–1.06), GSTP1 (OR: 0.82, 95% CI 0.74–0.90), and CTSS (OR: 0.91, 95% CI 0.88–0.95) may serve as potential therapeutic targets in prostate cancer." (PMID 37735436, 2023).